MTOR (mechanistic target of rapamycin kinase)
Diseases named in the same sentence as MTOR in open-access papers (continued):
Sharing a sentence is not in itself a finding about the gene and the disease.
cancer (continued). "Notably, recent studies also reported that upregulation of YAP1 is involved in cancer metabolism and mTOR activation by altering specific genes involved in metabolic pathways." (PMID 34003553, 2021). "Accordingly, we suggest that a deepening analysis of mTOR pathway regulation in ESCs, especially during diapause, could have important implications on our understanding of the phenomenon of cancer cell dormancy." (PMID 34832087, 2021). "For instance, the direct role of STAU1 in upregulating the mTOR pathway may positively impact formation of SGs and further promote cancer cell growth and survival." (PMID 34633481, 2021). "Indeed, pharmacological inhibitors of Akt/mTOR signaling, through regulation of autophagy, have emerged as promising approaches for therapeutics against cancers or liver diseases." (PMID 33828998, 2021). "Activation of the Akt/mTOR/S6 signaling is common in a wide range of cancers." (PMID 33921340, 2021). "Moreover, lncRNAs mediated inhibition or progression of cancer is regulated by mTOR-dependent or independent autophagy pathway." (PMID 34174900, 2021). "Accordingly, mTOR inhibitors have been shown to increase ROS levels in cancer cells." (PMID 33754064, 2021). "We next determined whether targeting STAT3 and the PI3K/mTOR pathway simultaneously blocked the feedback activation of STAT3 and sensitized PTEN-deficient cancer cells to BEZ235." (PMID 33431808, 2021). "Akt/mTOR pathway is one of these elements that is commonly dysregulated in cancer cells." (PMID 34669780, 2021). "In radiation-tolerant OSCC cells, BTK may be involved in the EGFR/AKT/mTOR signaling pathway and increase the drug sensitivity of cancer cells after radiotherapy." (PMID 33640903, 2021). "Inhibition of mTOR is, therefore, an important therapeutic target for cancer treatment." (PMID 34093717, 2021). "The phosphatidylinositol 3-kinase (PI3K)/serine-threonine kinase (Akt)/mammalian target of the rapamycin (mTOR)-signaling pathway has been suggested to have connections with the malignant transformation, growth, proliferation, and metastasis of various cancers and solid tumors." (PMID 34452154, 2021). "However, clinical studies have shown that mTOR inhibitors have some limitations, such as low bioavailability and toxicity, and some cancers eventually acquire drug resistance." (PMID 34123955, 2021). "Genetic or epigenetic changes to key mTOR pathway proteins may lead to cellular metabolic instability and human diseases, particularly cancers." (PMID 33668092, 2021). "The activation of the PI3K/AKT/mTOR pathway is able to modulate TGFβ signalling in cancer." (PMID 34944870, 2021). "Therefore, inhibiting PI3K/Akt/mTOR axis has been disclosed as a promising therapeutical goal for cancers." (PMID 34691211, 2021). "Therefore, from the perspective of immunity, the mTOR pathway is still a cancer pathway, which cannot support the previous conclusions obtained by studying the mTOR-score-related survival curve in KIRC." (PMID 34194607, 2021). "However, while waiting for further well-designed multicenter studies delineating the use of mTOR inhibitors, an attempt in implementing strategies to reduce CNIs in order to limit the impact of their exposure on cancer recurrence is reasonable." (PMID 34638365, 2021). "Downregulation of the mTOR network downstream activity increases longevity in several animal models from yeast to mice, whereas mTOR activation shortens longevity accelerating aging and the appearance of age-related degenerative diseases, including cancer and neurodegeneration." (PMID 34057907, 2021). "It has anticancer activity, reduces mTOR signaling, inhibits the proliferation of cancer cells in cell culture and suppresses the growth of various tumors (including luminal ER-positive breast tumors) in murine cancer models." (PMID 34201429, 2021). "Therefore, the relative activity of AMPK/mTOR in cancer cells plays a critical role in the initiation of autophagy and apoptosis." (PMID 34326874, 2021).
cancer (continued). "PI3K/AKT/mTOR pathway is frequently activated in various human cancers, contributing to diversiform oncogenic transformation processes (such as stimulation of proliferation, survival, metabolic reprogramming, metastasis, and inhibition of apoptosis, autophagy, and aging)." (PMID 33842367, 2021). "Metformin may inhibit cancer cells through various other mechanisms, such as mTOR pathway inhibition and autophagy induction." (PMID 34067321, 2021). "The phosphatidylinositol 3‐kinase (PI3K)/AKT/mTOR pathway (mammalian target of rapamycin) is activated in most human cancers, which plays an important role in numerous cellular functions including metabolism, proliferation, adhesion, migration, invasion, survival and angiogenesis." (PMID 34120414, 2021). "mTOR signaling is upregulated in many cancers, and the mTOR kinase central to the pathway has been a successful target of other cancer treatments, including in the treatment of subependymal giant cell astrocytomas (SEGAs) in another Ras pathway disorder, tuberous sclerosis complex (TSC)." (PMID 34885143, 2021). "The deregulation of the mTOR signaling pathway in many cancers suggests that mTOR inhibitors may have broad therapeutic use in various tumor types." (PMID 35155187, 2021). "Dapagliflozin, another SGLT2 inhibitor, could inhibit tumor growth and cancer proliferation by targeting the adenosine 5‘-monophosphate (AMP)-activated protein kinase (AMPK)/mammalian target of rapamycin (mTOR) pathway." (PMID 34948132, 2021). "PI3K/AKT/mTOR pathway is usually activated in various tumors, meanwhile, activating mutation of the PI3K genes (commonly the PIK3CA gene) were frequently seen in human cancers." (PMID 33613746, 2021). "From the KEGG pathway enrichment analysis results, we found that the DEARGs were enriched in pathways in cancer, regulation of autophagy, mTOR signaling pathway, NOD-like receptor signaling pathway, and Toll-like receptor signaling pathway, mainly related to cancer and immunity." (PMID 33706714, 2021). "Activation of p38 and inhibition of PI3K/Akt/mTOR induced by these materials in cancer cells can induce pro-apoptotic changes, cell cycle arrest, the autophagic process, and downregulate cell migration, resulting in both cellular proliferation suppression and metastasis inhibition." (PMID 34371964, 2021). "Molecular docking showed that Rg3 has a good binding score with Rheb and could thus decrease the signalling of mTOR axis, the inhibition of which is important in cancer treatment." (PMID 34208799, 2021). "The mammalian target of rapamycin (mTOR) regulates, among others, aerobic glycolysis in carcinomas." (PMID 33805626, 2021). "PSMD7 is reported to be overexpressed in most carcinoma cells and its down-regulation contributed to decelerated tumor growth, inhibition of proteasomal function, induced cell apoptosis and attenuated activity of the mTOR/p70S6K pathway." (PMID 33391408, 2021). "Moreover, the mTOR signaling pathway was found to upregulated in several carcinomas, including HCC, where overexpression of S6K was recorded in nearly half of the studied HCCs." (PMID 34049576, 2021). "We suggest that +mTOR is effective for both the OXPHOS cancer type and the glycolysis cancer type." (PMID 32276228, 2020). "Besides, NO participates in cancer-associated signaling pathways, including Wnt, Ras, ERK, Akt, cyclin D1, mammalian target of rapamycin (mTOR), and retinoblastoma (Rb) pathways." (PMID 32668616, 2020). "mTOR belongs to the PI3K-AKT-mTOR signaling pathway, which is strongly involved in many cancers." (PMID 33014785, 2020).
cancer (continued). "AURKA overexpression enhances cell survival by suppressing autophagy through activating the mammalian target of rapamycin (mTOR) signaling, activating anti-apoptosis signaling, and/or cancer cell survival and chemoresistance by activating of PI3K/Akt/GSK3 and NF-κB signaling cascades." (PMID 33353031, 2020). "However, it is also known that mTOR inhibition induces drug resistance through autophagy induction in cancer cells." (PMID 32260198, 2020). "mTOR inhibitors (rapamycin and its analogs also known as rapalogs) belong to the target drugs that are widely used in the treatment of the different types of cancer including breast cancer." (PMID 32825760, 2020). "Amino acids, including leucine and glutamine, are necessary for cell growth and proliferation, processes augmented in cancer cells and controlled by mechanistic target of rapamycin (mTOR) regulating cell growth, what leads to protein translation and macrophagy inhibition." (PMID 33195271, 2020). "Interestingly, QGP-1 spheroid cells, which exhibited cancer stem cell-like features in vitro and in a xenograft model, expressed low levels of Prdx2 and exhibited low activation of mTOR-related signaling pathways." (PMID 33182509, 2020). "However, recently studies indicated that Mammalian target of rapamycin (mTOR) is usually frequently deregulated in many cancers, especially in GC." (PMID 32769866, 2020). "Thus, it is inferred from these results that RP4010 inhibits cancer cell proliferation and colony formation through the inhibition of calcium-regulated Akt/mTOR and NFAT signaling." (PMID 32235707, 2020). "In the clinic, a phase I trial (NCT00949949) was performed to determine the maximum tolerated dose (MTD) of mTOR inhibitor everolimus (5 mg) combined with either gemcitabine (800 mg/m2, Cohort I) or gemcitabine plus cisplatin (12.5 mg/m2, Cohort II) in cancers." (PMID 33028805, 2020). "Mammalian target of rapamycin (mTOR) hyperactivity may contribute to metabolic plasticity and progression in cancers." (PMID 32899149, 2020). "Moreover, KEGG analysis of the highly enriched gene pathways identified the phospholipase D signaling pathway, MAPK signaling pathway, mTOR signaling pathway, as well as genes involved in choline metabolism in cancer, and in glycerophospholipid metabolism." (PMID 32742484, 2020). "Emerging evidence from preclinical and clinical studies suggest that inhibitors of the PI3K/AKT/mTOR pathway could have potential in combination with other anticancer therapies to circumvent resistance by cancer cells." (PMID 33110476, 2020). "ASA activates AMPK, which modulates the mTOR pathway in various cancer cell types and may in part mediate its anticancer effects." (PMID 31906519, 2020). "Dysregulation of downstream kinases in PI3K/Akt/mTOR pathway are common in many types of cancer." (PMID 32131560, 2020). "In addition, KEGG pathway analysis revealed significant gene enrichment in the mTOR signaling pathway, integrin family cell surface interactions and pathways involved in cancer." (PMID 32793502, 2020). "Within diverse cancer types, miRNA expression profiles are substantially different compared to their normal tissue counterparts, and miR-21 overexpression directly activates aberrant mTOR signaling in many solid cancers." (PMID 33364499, 2020). "The polypyrimidine stretch proximal to the 5′ end of these genes is a target for translation regulation and has been suggested to serve as a target mechanism for oxidative and metabolic stress, or cancer-induced differential translational regulation by the mTOR pathway." (PMID 31924754, 2020).
cancer (continued). "The abnormal expression and activation of AXL provides cancer cells a survival advantage by activating the phosphatidylinositol 3-kinase (PI3K)/mammalian target of rapamycin (mTOR) and MAPK pro-survival pathways as well as pathways related to cell growth, migration, and invasion." (PMID 33283192, 2020). "The PI3K/Akt/mTOR signaling pathway is also associated with EMT, cancer invasion, and migration." (PMID 32549236, 2020). "Indeed PTEN, dimethylated at arginine 159 (R159) is mutated at R159 in cancers, losing the capability to inhibit the PI3K–AKT pathway targeting the mammalian target of rapamycin (mTOR)." (PMID 32708484, 2020). "mTOR inhibitors have been tested in many clinical trials in the context of other cancers, but they achieved only modest efficacy applied as monotherapies in cancer treatments due to resistance mechanisms." (PMID 32517736, 2020). "miR-99a functions as a tumor suppressor in various cancers by targeting the mTOR signaling pathway." (PMID 32605105, 2020). "The AKT/mTOR signaling pathway is commonly activated in different cancers, including RB." (PMID 33204686, 2020). "In addition to the cell cycle pathway, SKP2 also participates in other cancer hallmark pathways such as FOXO, AMPK/mTOR, AKT, apoptosis and Hippo signaling pathway 15-18, 20, 21, 28-32." (PMID 32226545, 2020). "Activation and mutations of PI3 kinase (PI3K), mTOR, insulin-like growth factor (IGF-1), epidermal growth factor receptor (EGFR), and NF-κB pathways have all been identified in several human disorders, especially cancer." (PMID 33013390, 2020). "Moreover, the PI3K/Akt/mTOR signalling pathway has been extensively confirmed to be critical for radiotherapy resistance in various cancer types." (PMID 32239160, 2020). "The targeted degradation of Akt and mTOR in cancer may open new avenues and improve efficacy of treatment." (PMID 32012648, 2020). "Decline in its expression may lead to a decrease of hypoxia ability to inhibit mTOR, thereby affecting the pace of development of the cancer." (PMID 31952173, 2020). "mTOR inhibitors are therefore considered a valuable addition to chemotherapy or targeted cancer therapy, either as an option for relapsed patients or as a frontline combination therapy to prevent or delay the development of resistance due to sustained mTOR signaling." (PMID 32943635, 2020). "Several studies have reported that simultaneous inhibition of EGFR and mTOR could provide a synergistic antitumour effect in various human cancers, including TNBC20–23." (PMID 32286420, 2020). "In addition, we explored the role played by members of the NF-κB family in cancer hallmark pathways, including TSC/mTOR, RTK, RAS/MAPK, PI3K/AKT, hormone ER, hormone AR, EMT, DNA damage response, cell cycle, and apoptosis." (PMID 32879628, 2020). "Accumulating studies have revealed that PI3K/AKT/mTOR acted as key drivers of cellular growth, adhesion, migration, and survival in human carcinogenesis, including CRC, in which the activation of PI3K/AKT/mTOR signaling supports cancer cell growth, metastasis, and drug resistance." (PMID 33193658, 2020). "The KEGG pathway analyses showed that the hub genes were involved in the cancer pathway, cAMP signalling pathway, mTOR signalling pathway, VEGF signalling pathway, aldosterone‐regulated sodium reabsorption, WNT signalling pathway, Ras signalling pathway and HIF‐1 signalling pathway." (PMID 32410228, 2020). "Indeed, mTOR inhibitors have been approved for the cancer treatment of renal cell carcinoma and mantle cell lymphoma and are in clinical trial for other indications." (PMID 33297429, 2020). "Notably, FBXW7 ubiquitinates and degrades mTOR, and loss or mutation of FBXW7 increases the sensitivity of cancer cells and mouse models to rapamycin." (PMID 33291075, 2020).
cancer (continued). "Interestingly, dissecting up- and down-regulated processes revealed the involvement of distinct early disease-related changes including mitochondrial dysfunction, cancer pathways, mTOR signalling and developmental processes." (PMID 32938982, 2020). "In addition, RE significantly reduced the phosphorylation/activation and total levels of Akt and mTOR, key players controlling cancer cell proliferation and survival." (PMID 32012648, 2020). "In summary, our study reveals an exciting, ambivalent function of mTOR, which renders tumor cells resistant to chemotherapy and targeted cancer drugs, but simultaneously suppresses autophagy, an essential survival mechanism for coping with therapy-induced metabolic perturbations." (PMID 32943635, 2020). "The mTOR complexes play an important role in cancer metabolism." (PMID 32051833, 2020). "Understanding how mTORC1 activity is regulated by glucose is not only important to better delineate the biological function of mTOR, but also to highlight potential therapeutic strategies for treating diseases characterized by deregulated glucose availability, as is the case of cancer." (PMID 32351714, 2020). "Target selection for miR-100 was more challenging as there are far less validated targets and even less related to cancer progression, thus we analyzed the validated survival related target mammalian target of rapamycin (mTOR), as well as Ago1 and Ago2 which are predicted targets of miR-100." (PMID 32872485, 2020). "Moreover, in the results of miR-581 target genes, TNFSF10, HMGA2, CEACAM1, and mTOR have been reported to be involved in proliferation and apoptosis in a number of cancers." (PMID 32899503, 2020). "The gene network of AKT1/mTOR signaling pathway plays a crucial role in cancer development." (PMID 33247671, 2020). "Therefore, future laboratory as well as clinical research in this area should focus on the translational potential of dual PI3K and mTOR inhibitors as radiosensitisers in cancer patients." (PMID 32443649, 2020). "An elegant work recently using whole-genome RNAi screening identified MTOR as a common orchestrator in stress-induced genomic instability, accelerating the adaptation of cancers in cytotoxic condition and facilitating the cancer resistance to different oncotherapy." (PMID 33330109, 2020). "Moreover, combined therapy of nelfinavir and mefloquine (an analogue of chloroquine) or salinomycin (an anti-cancer antibiotic) resulted in activation of the ATF4-CHOP-GADD34 arm of the ER stress pathway in Tsc2−/− mTOR-hyperactive cells." (PMID 33228205, 2020). "The PI3K/AKT/mTOR pathway has an important effect on regulating autophagy, proliferation, apoptosis and so on, sequentially affecting the occurrence and development of cancer 29-32." (PMID 32284762, 2020). "Here, we report that the PI3K/AKT/mTOR signaling pathway, which is frequently hyperactivated in cancer, also exhibits an important role in CTCs and may be a valuable target for anti-cancer therapies." (PMID 32962206, 2020). "HIF-1α could also be activated by the PI3K/AKT/mTOR signaling pathway, which is upregulated in numerous cancers including GRM1-expressing melanoma cells." (PMID 32937954, 2020). "Abnormal mTOR signals can be observed in different types of cancer." (PMID 32082999, 2020). "Moreover, MNKs seem to play an important role in the interplay between the Ras/MNK and PI3K/AKT/mTOR pathways, two critical signaling pathways involved in tumorigenesis and chemoresistance that are frequently deregulated in a broad variety of cancers." (PMID 32340135, 2020). "AMPK was downregulated by PDP1 overexpression, resulting in mTOR activation and cancer progression." (PMID 32782783, 2020). "The PI3K/Akt pathway is involved with mTOR signaling, which is downstream and represents one of the frequently deregulated pathways in cancer cells, and one of the most important targets of new cancer therapies." (PMID 32178280, 2020).